AR (androgen receptor)
Diseases named in the same sentence as AR in open-access papers (continued):
Sharing a sentence is not in itself a finding about the gene and the disease.
tumor (continued). "Enhanced FGF signaling plays an important role in tumor progression and drug resistance, which can induce angiogenesis, epithelial-to-mesenchymal transition (EMT), and upregulation of AR." (PMID 37179366, 2023). "One well-established co-repressor of the AR is prohibitin (PHB), which was discovered in the 1980s as possessing tumour suppressor functions." (PMID 37373067, 2023). "This stemness gene suppression suggests the possibility of using a continuum of Top2 catalytic inhibitors in the progression of PCa disease with the synergism of an EZH2 degrader in AR-dependent PCa cells and EZH2 catalytic inhibitors in NEPC tumor cells." (PMID 36678591, 2023). "The androgen receptor promotes GPX4 overexpression in the luminal androgen receptor subtype of TNBC, which assists tumor cells in escaping ferroptosis." (PMID 37064872, 2023). "The androgen receptor (AR) is expressed in up to 50% of TNBCs, and AR inhibition decreases CSC and tumor initiation." (PMID 36766786, 2023). "A novel tumor-suppressor, lncRNA NXTAR, has recently been found to suppress AR expression through recruiting EZH2 methyltransferase." (PMID 36674820, 2023). "Activation of the androgen receptor, NOTCH, and ESR1 signaling affects several aspects of breast carcinogenesis, from tumor development to progression and metastatic outgrowth through genomic and non-genomic pathways." (PMID 37958677, 2023). "In the luminal AR subtype of TNBC, which shares similarities with molecular apocrine tumors, the AR appears to drive tumor progression." (PMID 37681860, 2023). "AR protein levels are higher in HCC than in adjacent tissues, and higher AR levels correlate with increased tumor recurrence and decreased overall survival." (PMID 37626712, 2023). "AR activation by dihydrotestosterone (DHT) induces RUNX1 gene expression in vitro and in vivo in AR+-TNBC PDX tumor samples." (PMID 36766786, 2023). "The experiments also showed that the switch between AR signaling and EGFR signaling is mediated by HS3ST1 in tumor formation and growth." (PMID 37463954, 2023). "In the tumor tissues of NEPC patients, AR signaling is low or lost, and such typical NE markers as neuronal-specific enolase 2 (ENO2), synaptophysin (SYP), NCAM1 and chromogranin A(CHGA) are remarkably elevated." (PMID 37563661, 2023). "Correlations of tumor clinicopathological characteristics with ERα, ERβ, PGR, and AR protein expression in malignant colonic tissues from male (n = 64) and female (n = 56) patients by Pearson’s correlation test." (PMID 37206439, 2023). "Aberrant MYB expression begins early in preneoplastic HGPIN, increases with advancing tumor grades and pathological stages, exhibits correlative expression with AR, and serves as a better predictor of BCR than nuclear AR and Gleason’s grades." (PMID 38089573, 2023). "Further, olaparib plus enzalutamide treatment inhibited PC tumor growth in subcutaneous patient-derived xenograft tumor models (MDA PCa 133-4, AR-positive) as well as in two orthotopic PC cell lines (AR-positive VCaP and CWR22Rv1)." (PMID 37152924, 2023). "We further studied the effect of AR knockdown on AR, FEN1, pho‐ERK1/2 and pho‐ELK1 expression in tumour tissues by Western blot." (PMID 37326412, 2023). "Clinical: serum CA 15-3, CA125, family history of BC, body mass index (BMI), carcinoembryonic antigen (CEA) levels.Pathological: ER, PR, HER2 status, Ki67, Lymphovascular invasion (LVI), and AR.Radiomics: TTP, tumor volume, and maximum tumor diameter." (PMID 37958461, 2023). "Activated AR also directly stimulates the expression of FASN and of numerous other genes involved in the fatty acid synthesis, and this promotes tumor growth, as evidenced in a variety of preclinical models." (PMID 36768610, 2023).
tumor (continued). "Panobinostat, an HDACI, has been proven to reduce AR mRNA levels, including ARV7, as well as cell proliferation in vitro and tumor growth in vivo in all CRPC model systems." (PMID 37189723, 2023). "In support of these results, an inverse correlation between the staining intensity of ADORA2A and a typical AR target, PSA, was identified in human PCa tumor sections." (PMID 38099497, 2023). "Correlations of tumor clinicopathological characteristics with ERα, ERβ, PGR, and AR protein expression in malignant colonic tissues from all patients (n = 120) by Pearson’s correlation test." (PMID 37206439, 2023). "As anti-androgen therapy is a preferred clinical treatment option in AR-positive TNBC, we compared the test compounds with clinically relevant anti-androgen, ENZ and chemotherapeutic, DTX, which inhibited tumor growth by 78.6% and 74.9%, respectively." (PMID 37766871, 2023). "Functioning as a tumor suppressor, FOXO1 can be recruited by liganded AR to the chromatin containing its target gene promoters, where it interferes with AR-DNA interactions and disrupts ligand-induced AR subnuclear compartmentalization." (PMID 36831629, 2023). "In concordance with the tumor responses to SPT, SPT resulted in a larger decrease in expression of the AR-biphasic genes enriched for cell cycle and E2F targets and of G2M checkpoint genes in R tumors than in NR tumors." (PMID 35603787, 2022). "An immunohistochemical analysis of metastasis samples was performed to assess tumour cell proliferation (percentage of Ki67-positive cells) and the expression levels of prostate-specific antigen (PSA) and androgen receptor (AR)." (PMID 36743403, 2022). "We aimed to determine the role of the androgen receptor signaling pathway (ARSP)-related lncRNAs in the incidence and progression of BRCA and their relationship with the tumor microenvironment (TME)." (PMID 36450882, 2022). "In the present study, patients with AR normal at baseline showed benefit on median OS and PFS with docetaxel or abiraterone or enzalutamide independently from GG of the primary tumor." (PMID 35513478, 2022). "Treatment with BETs and PLK1 dual inhibitor WNY0824 significantly suppresses AR-positive CRPC cell proliferation in vitro and xenograft tumor growth in animal models." (PMID 35335873, 2022). "Immunohistochemistry staining for AR confirmed that DHT effectively induced AR to translocate into the nucleus, while HC-1119 treatment largely blocked DHT-induced nuclear localization of AR in the xenograft tumor cells." (PMID 35960413, 2022). "A recent study found higher expression levels of nuclear receptor-interacting protein (NRIP) and androgen receptor (AR) and lower DDB2 expression in PC tissues than in non-tumor tissues." (PMID 36190612, 2022). "In vitro, the pharmacological inhibition of the AR pathway and PI3K pathway resulted in a potentially synergistic tumor reduction of 84%." (PMID 36551776, 2022). "On the other hand, HER2 is post-translationally repressed by the AR, and ADT removes this repression leading to its increased in situ expression in advancing disease and tumour recurrence." (PMID 35326402, 2022). "Herein, we demonstrate that enzalutamide and AR-directed antisense oligonucleotides (AR-ASO) block 5α-dihydrotestosterone (DHT)-induced DSRCT cell proliferation and reduce xenograft tumor burden." (PMID 35650195, 2022).
tumor (continued). "Using two orthogonal CRISPR drop-out screens tiling 878 sgRNAs across the entire AR enhancer region on ChrX13, AR13 (found in 13 primary tumors) proved most-critical for tumor cell proliferation, in contrast to the more-commonly shared AR23 or less-common AR2." (PMID 36450752, 2022). "Treatment with (R)-12 suppresses ERG, Myc and AR signaling, and inhibits CRPC cell proliferation, colony formation, and tumor growth." (PMID 35335873, 2022). "Overall, however, the median tumor cell proliferation was significantly lower in primary tumors than in metastases, while the median PSA and AR staining scores were significantly higher." (PMID 36358614, 2022). "The AR can also up-regulate tumor suppressor genes, such as the tumor suppressors SEC14L2, EAF2 and ZBTB16, to repress tumor growth directly." (PMID 36499670, 2022). "In each of these models, 25 tumor‐bearing mice were randomly divided into 5 groups and treated every three days for three weeks with PBS, bare Au nanoparticles, the Au‐AR pep‐PROTAC drug, Au‐Peptide Control, or enzalutamide at the same dose (2 mg kg−1)." (PMID 35971165, 2022). "Primary PCa tumor cells display unusual high oxidative respiration levels, which switch in CRPC cells to high aerobic glycolysis upon androgen-independent AR signaling." (PMID 35692804, 2022). "A phase 1 study tested the anti-tumor activity of Seviteronel, a selective CYP17 lyase and AR inhibitor." (PMID 36111296, 2022). "Lower testosterone serum levels might enhance the androgen receptor sensitivity on T cells and also the conversion rate of testosterone to dihydrotestosterone, which enhances binding to the androgen receptor, and the individual tumor tissue may play an important role." (PMID 35625643, 2022). "Detection of tumor type-specific alterations, including AR, ESR1, GNAS, and EGFR alterations in seven samples, as well as EBV, HBV, and MSI positivity in three samples, informed potential tumor origins." (PMID 35486650, 2022). "Biological insight into AR-positive TNBC has positive significance for signaling pathway cross-talk, TNBC subtype classification, early tumor detection, and synergistic treatment." (PMID 36188535, 2022). "In contrast, high tumor cell Ki67 labeling (proliferation) in combination with low tumor cell immunoreactivity for PSA, and a low fraction of AR positive stroma cells in the primary tumors were prognostic for poor survival after ADT." (PMID 36358614, 2022). "In their findings, AR expression was negatively correlated with ASS1 expression, thus contributing to RCC tumor progression." (PMID 36430837, 2022). "Androgen receptor (AR), which is expressed in 10–50% of TNBC, can stimulate tumor cell growth in TNBC10,11." (PMID 36577919, 2022). "Since treatment naïve PCa is predominantly AR and PSA positive tumours, the presentation of ARLPC, SCNPC, and DNPC at the late stage of tumour progression suggests that AR bypass mechanisms are adopted by these tumours." (PMID 35832549, 2022). "If ECM stiffening is effectively involved in CRPC through both AR-dependent and AR-independent mechanisms, targeting either the ECM stiffening or the tumor cell mechanosensing abilities is tempting." (PMID 35740556, 2022). "Early studies into AR mRNA expression within HCC found high between subject variability of AR mRNA and higher AR mRNA levels in tumor as compared to adjacent normal tissue." (PMID 36430245, 2022). "Using multiplex immunofluorescence staining, we detected AR and SYP simultaneously in tumor samples consisting of both premalignant prostate lesions and malignant tumor tissues." (PMID 36033483, 2022). "Hence, the AR–GR interaction might be also important in tumor development." (PMID 35761157, 2022). "Defining the specific tumor molecular profile including PDL-1 and androgen receptor testing is expanding treatment options in the clinical setting." (PMID 35267561, 2022).
tumor (continued). "Hormone- and context-dependent activities of these master regulators further involve pioneer factors that mediate AR-driven transcriptional programming; GATA2, FOXA1, and HOXB13 drive lineage-specific gene expression that is critical for tumor development." (PMID 36181613, 2022). "We conclude that outcome after ADT and metastasis subtype can, at least to some extent, be predicted by analysis of primary tumor characteristics, such as tumor cell proliferation and PSA expression, and AR expression in stromal cells." (PMID 36358614, 2022). "Since the biochemical, cytological, and molecular data demonstrated AR as the prime target of VNPP433-3β, we sought to evaluate the effect of VNPP433-3β in AR-overexpressing tumor xenografts in vivo." (PMID 36078112, 2022). "Primary GBM tumors have so far been shown to express AR, and overexpression of this receptor’s mRNA has been reported in GBM tumor tissue." (PMID 36361793, 2022). "In this study, we also examined stromal AR action in Gli1-lineage cells to promote PIN and tumor progression by injecting TM to 2-month-old Hi-Myc:ArL/Y:Gli1CreER/+ and Hi-Myc:Gli1CreER/+ mice and analyzed them at 6-months of age." (PMID 36323713, 2022). "In addition, M2-polarized tumor-associated macrophages and myeloid-derived suppressor cells are also detectable in the PCa TME, with the latter producing IL-23, which has been shown to be involved in the regulation of castration resistance by sustaining AR signaling." (PMID 35955671, 2022). "Curcumin blocked the occupancy at sites of AR function by interacting with cAMP response element binding protein (CBP) and co-activator protein p300 in LNCaP and PC-3 cells, thus decreasing tumor growth and delaying the onset of hormone-resistant disease." (PMID 36139145, 2022). "Meta-analysis showed that AR-positive TNBC patients had more metastasis to lymph nodes and lower tumor grade." (PMID 35203574, 2022). "This study ultimately led to other phase II clinical trials investigating the anti-tumour activity and safety of other anti-androgen agents such as enzalutamide and abiraterone acetate (a selective inhibitor of CYP17) among AR-positive TNBC patients." (PMID 35877237, 2022). "A total of 695 BCs were selected and reviewed, AR, ER, PR and HER2 expression in tumor cells were examined by immunohistochemical method, and the SISH method was used in case of HER2 with equivocal immunohistochemical score (2+)." (PMID 35052843, 2022). "Tumours showed robust downregulation of SWI/SNF targets and AR, ERG, MYC and Ki67 after five days of AU-15330 treatment, both when administered alone or with enzalutamide." (PMID 34937944, 2022). "Compared with the saline group, the tumor weights of the Taxotere, Di-PP/AR-siRNA, Di-PP/DTX, PP/AR-siRNA/DTX, and Di-PP/AR-siRNA/DTX groups were all significantly reduced." (PMID 35631549, 2022). "AR antagonists, upon binding to AR’s LBD, promote corepressor recruitment to DNA-bound AR, which in turn triggers regulatory events that lead to androgen action suppression and tumor growth reduction." (PMID 35205640, 2022). "Intriguingly, oestrogen receptor beta was shown to act as a tumour suppressor in GBM by downregulating DNA damage response, which confers the opposite effect to AR signalling." (PMID 35661403, 2022). "To verify the potential impact of glycemic metabolism and genomic alterations, we performed immunohistochemistry analysis for AR, IR-α, IR-β, IGF1-R and PSMA expression in the primary tumor." (PMID 36077746, 2022).
tumor (continued). "The expression of both hARtg and mGFP in atypical and tumor cells within HGPIN and PCa lesions demonstrate the critical role of transgenic AR in Osr1-lineage cells in inducing prostatic oncogenesis and promoting PIN and PCa development." (PMID 35902588, 2022). "Among the 94 patients studied, CK 5/6 staining was seen in the cytoplasm of the tumour cells in 31 patients (33%), EGFR in 47 patients (50%), E-Cadherin in 32 patients (34%) and Androgen receptor in 32 patients (34%)." (PMID 35463732, 2022). "In PCa, the AR and PI3K/Akt pathways are considered the major drivers of tumor growth and progression." (PMID 35310915, 2022). "In primary tumors, SMA+ smooth muscle cells (generally AR+), SMA+ fibroblasts (CAFs) and SMA+ cells in blood vessel walls were all common and constituted almost 1/5 of the tumor volume, while in the bone metastases, SMA+ cells were significantly less abundant." (PMID 36358614, 2022). "Another novel AR antagonist, SHR3680, preclinically has shown anti-tumor potency comparable to enzalutamide but with a reduced distribution in the brain and significantly decreased risk to induce a seizure." (PMID 35864113, 2022). "A NXTAR gene-specific oligonucleotide led to the reduction in AR/AR-V7 and proliferation of PCa cells, while in a xenograft study, a small-molecule AR inhibitor restored NXTAR expression and blocked the tumor growth of enzalutamide-resistant PCa." (PMID 35205640, 2022). "6PGD was very recently reported to enhance the stability of androgen receptor (AR) protein, revealing a positive feedback loop between androgen signaling and the PPP, which enhances growth and survival of tumor cells." (PMID 35498409, 2022). "Tumor cells exhibited a uniform strong cytoplasmic immunoreactivity for ALK, expressed AR and NKX3.1 but were negative for the neuroendocrine marker synaptophysin." (PMID 36337169, 2022). "The tumor cells were positive for arginase-1, CD10 (with canalicular enhancement), CD56, cytokeratin 8/18/19, Hep Par-1, β-catenin, LEF1, and androgen receptor (weak positivity)." (PMID 35359182, 2022). "This study aimed to characterize the dynamic response of prostate tumors to enzalutamide, a current generation AR antagonist, and to demonstrate the functional significance of IL8 and VEGF signaling in modulating the adaptive tumor response." (PMID 35302608, 2022). "During the pathological process, ADAMTS-1 can cleave or induce the release of proangiogenic factors (IGFBP2, HB-EGF, AR) and degrade ECM components, such as versican, to facilitate tumor invasion." (PMID 36338393, 2022). "These epigenetic enzymes can be inhibited by a CellCentric developed compound, CCS1477, where administration of CCS1477 was shown to downregulate the expression of AR and MYC, resulting in decreased tumor growth in a 22Rv1 xenograft model of CRPC." (PMID 35547880, 2022). "Therefore, a consequence of AR-targeted therapy-induced hypoxia may be to increase CXCR2 expression in tumor cells, which by extension results in the selection of cells undergoing transition to neuroendocrine prostate cancer, a known driver of castration-resistance." (PMID 35302608, 2022). "Activated AR in complex with FOXA1 can drive transcription of Myc, Wnt7B and Her3, representing pathways directing tumor survival, stemness and proliferation." (PMID 35203574, 2022). "However, androgens may have a proliferative effect through AR in ER- AR+ tumor cells." (PMID 35052843, 2022). "This study aimed to determine the mechanism of how AR represses GPER1 and thereby by-passes the tumor suppressive action of G-1 treatment in CRPC." (PMID 35018219, 2022).